LAIR1 (leukocyte associated immunoglobulin like receptor 1)
Diseases named in the same sentence as LAIR1 in open-access papers (continued):
Sharing a sentence is not in itself a finding about the gene and the disease.
cancer (continued). "It is hypothesized that a link may be found between LAIR-1 expression and HDL-C during HCC development post-HCV treatment as a previous Mendelian meta-analysis reported that a 1-mg/dL reduction in the HDL-C level was associated with a 14% increased overall cancer risk." (PMID 36293412, 2022). "We found that in some cancers, especially in LUAD and TGCT, FH expression was significantly correlated with multiple immune checkpoint markers, such as BTLA, TNFRSF14, LAIR1, CD48, and CD28." (PMID 34737838, 2021). "FTH1 levels were positively related to PD-1 in 4/32 (12.5%) cancers, PD-L1 in 9/32 (28.1%), CTLA4 in 7/32 (21.9%), TIM-3 in 20/32 (62.5%), LAG3 in 2/32 (6.3%), and LAIR1 in 19/32 (59.4%)." (PMID 33864445, 2021). "We found that FTL levels were positively related to PD-1 in 14/32 cancers (43.8%), PD-L1 in 10/32 (31.3%), CTLA4 in 13/32 (40.6%), TIM-3 in 26/32 (81.3%), LAG3 in 13/32 (40.6%), and LAIR1 in 26/32 (81.3%)." (PMID 33864445, 2021). "Our findings demonstrate that LAIR1 expression is induced following CD18 interaction specifically with collagen, further characterizing cancer’s ability to commandeer normal wound healing processes and tissue-based immune homeostasis to evade destruction." (PMID 32908154, 2020). "Particularly, SPARC and SPP1 expression were positively correlated to DC-related markers CD86, NRP1, and inhibitory checkpoint markers including LAIR1, HAVCR2, and PDCDLG2 in most cancer types." (PMID 33240930, 2020). "These coordinated effects by anti-Lair1 antibody highlight the benefits of targeting these elements within the TME and provide insight into the utility of an integrated approach for better therapeutic intervention in cancer treatment." (PMID 40591413, 2025). "LAIR1+ cells extended beyond GBM and were observed in various cancer tissues." (PMID 40591413, 2025). "Other groups have also used LAIR1 KO, anti-LAIR1 antibodies, and LAIR2 to treat cancer." (PMID 40829176, 2025). "Other immunotherapeutic strategies under study for MSI-H cancers include vaccines, systemic immunomodulators, STING agonists, PKM2 activators, T-cell immunotherapy, LAIR-1 immunosuppression reversal, IL5 superagonists, oncolytic viruses and IL12 partial agonists." (PMID 38254772, 2024). "For the various types of cancer featured in this review, collagen I interacts with various receptors on cancer cells (including integrinβ, Endo180 or uPARAP, DDR, LAIR-1, CXCR2 and CXCR4), opening interesting perspectives for the development of new drugs targeting such interactions." (PMID 37373151, 2023). "Recently, we observed that LAIR‐1 expression was detected in HCC but not in healthy liver tissues, and high LAIR‐1 expression was related to unfavorable cancer differentiation." (PMID 37647449, 2023). "To identify potential therapeutic targets of those cancers and immune escape, we have collected more than forty representative immune checkpoint genes, including BTLA, CD200, TNFRSF14, NRP1, LAIR1 and so on, and we evaluated the relationship between expression of COL1A1 and immune checkpoint." (PMID 35789341, 2022). "Overall, our study shows that collagen fragments produced in cancer can mediate LAIR-1 induced T cell suppression, and that blocking this interaction with LAIR-2 fusion proteins could be of importance for cancer treatment." (PMID 34691040, 2021). "Actually, both C3 and LAIR1 genes connect with the transcription factor CREB (cyclic AMP response element binding protein), which has a role in the pathogenesis of AML and other cancers." (PMID 31533352, 2019). "The findings suggest that LAIR1 inhibition, either through antibody blockade or a CAR design, could serve as a standalone treatment or be combined with other therapeutic approaches for effective cancer treatments." (PMID 40591413, 2025).
cancer (continued). "In an all-encompassing vision of collagen action, it was observed that the cancer phenotype resulting from abnormal collagen production, which interferes with immunity activation acting as a barrier, overlap with phenotype resulting from ECM receptors signaling (i.e., LAIR-1 and Integrins)." (PMID 38969910, 2024). "The study found a negative correlation among STAAD cancer patients between NPRL2 expression and PDCD1LG2, LAIR1, and BTLA checkpoint markers." (PMID 39932765, 2025).
infection (6 papers, 2019 to 2025). The state of being infected such as from the introduction of a foreign agent such as serum, vaccine, antigenic substance or organism. "Early in infection, the increase in cell numbers was mostly contributed by enhanced neutrophil recruitment in LAIR-1-deficient mice, while at day 5 post-infection lymphocytes mainly constituted the infiltrating population." (PMID 31080449, 2019). "Lastly, we also assessed expression levels of LAIR1 on pDCs by flow cytometry of whole blood from eight SHIV-infected RMs at 16 weeks post-infection." (PMID 34181694, 2021). "Lair1 KO exhibited a pattern of increased inflammatory responses in infection and sterile immune stimulation, with increased production of proinflammatory cytokines and myeloid chemokines, neutrophil ROS, and collagen/ECM pathway proteins, including collagens and complement factors." (PMID 41231542, 2025). "Whereas the relative expression levels of CTLA-4 and LAIR-1 were increased on day 3 or 7 after infection in WT, KI, and KO mice, and their levels were significantly higher in WT mice than in KI or KO mice on day 7 after infection." (PMID 36275680, 2022). "Quantitative RT-PCR showed that the relative expression levels of immune checkpoint CTLA-4, LAIR-1, GITR, BTLA, TIM-3, or PD-1 mRNA in the lung presented decreased levels on day 3 or 7 after infection in KI or KO mice." (PMID 36275680, 2022). "IHC results showed that LAIR-1 positive cells could be found in WT, KO, or KI mice lung tissues with CA04 infection, and the positive cells were mainly distributed in an inflammatory dense area." (PMID 36275680, 2022). "However, upon infection with RSV, circulating neutrophils started to express LAIR-1." (PMID 31080449, 2019).
hematologic malignancies (4 papers, 2022 to 2025). "The study of this possibility should be faced before using the targeting of LAIR1 in hematological malignancies." (PMID 40563506, 2025). "In conclusion, there is clear evidence that LAIR1 represents in the oncologic field a very attractive therapeutic target for the treatment of hematologic malignancies for its strong expression confined to leukemic stem cells." (PMID 40563506, 2025). "In hematological malignancies, several studies have examined the potential implication of LAIR1 in tumorigenic processes." (PMID 36555775, 2022). "Using the Genomicscape webtool, we investigated the prognostic value of LAIR1 expression in different hematological malignancies." (PMID 36555775, 2022). "The roles of LAIR1, a classical ITIM-containing receptor, have been studied in hematologic malignancies and solid cancer." (PMID 36211388, 2022).
inflammation (2 papers, 2019 to 2021). Aberrant reaction of the microcirculation characterized by movement of fluid and leukocytes from the blood into extravascular tissues. "We found that LAIR-1 expression on both the total T cells and two T cell subsets was negatively correlated with liver inflammation (ALT, AST, and TBIL levels), serum HBV virological indexes (HBV DNA and HBV pgRNA levels), and fibrosis (FibroScan value and APRI score)." (PMID 34398030, 2021).
bacterial infections (1 paper, 2025). "Reasonably, further studies are needed to better define the functional significance of LAIR1 during bacterial infections." (PMID 40563506, 2025).
hematologic cancers (1 paper, 2023). "Clinical trials for LAIR-1, LILRB4 and DDR1 in solid and hematologic cancers." (PMID 37662958, 2023).
liver (1 paper, 2021). "In addition, LAIR-1 expression levels on CD3+, CD4+, and CD8+ T cells were all negatively associated with liver inflammation and fibrosis parameters, such as alanine aminotransferase and aspartate aminotransferase levels, FibroScan value, and aspartate aminotransferase-to-platelet ratio index score." (PMID 34398030, 2021).
LAIR1 also shares sentences with these, for which no sentence is quoted: acute myocardial infarction (2 papers); brain tumor (2); Immune Disorders (2); mixed connective tissue disease (2); systemic sclerosis (2); thymoma (2); adenocarcinoma (1); allergic asthma (1); Allergy (1); B cell lymphoma (1); brain cancer (1); Chronic Hepatitis B Infection (1); Cognitive impairment (1); colorectal cancer (1); Cutaneous T-cell Lymphoma (1); dyslipidemia (1); Epstein-Barr virus infection (1); esophageal cancer (1); fibrosis (1); generalized epilepsy (1); glomerulonephritis (1); hairy cell leukemia (1); head and neck squamous cell carcinoma (1); hematological neoplasms (1); Hodgkins lymphoma (1); IgA nephropathy (1); infectious disease (1); interstitial nephritis (1); invasive breast carcinoma (1); Lewis lung carcinoma (1).
A further 18 diseases each share a sentence with LAIR1 in 1 paper.